EGFR (epidermal growth factor receptor)
Diseases named in the same sentence as EGFR in open-access papers (continued):
Sharing a sentence is not in itself a finding about the gene and the disease.
cancer (continued). "Compensatory TK signalling is observed in EGFR-TKI therapy, and KRAS, anaplastic lymphoma kinase (ALK), c-MET and BRAF mutations are also associated with poor responses to anti-EGFR therapy in some cancers." (PMID 29527128, 2018). "Specifically, communication between the Notch and EGFR pathways in cancer cells enables the cells to compensate for the loss of one pathway with the increase in the other." (PMID 29321718, 2018). "Gefitnib was appraised by NICE to provide sufficient benefits given its costs for patients with advanced NSCLC who had cancer which tested positive for mutations which lead to overexpression of epidermal growth factor receptor (EGFR)." (PMID 29780892, 2018). "The loss of RARB expression has been associated with a variety of cancers (predominantly of mammary and pulmonary origin), and it has been correlated with suppressed expression of epidermal growth factor receptor (EGFR)." (PMID 29467946, 2018). "HER2 is a membrane-bound receptor tyrosine kinase belonging to the epidermal growth factor receptor (EGFR) family and is implicated as an oncogene in many human cancers." (PMID 29699519, 2018). "Cancer cells acquire resistance against EGFR inhibitor treatment via loss of IGFBP-3, which activates the IGF-1R signaling pathway." (PMID 29445126, 2018). "Gefitinib is indicated for the treatment of patients suffering from cancer due to EGFR mutations but with clinical treatment the drug resistance is found in most of patients." (PMID 29618949, 2018). "Afatinib also has high sensitivity to cancer cells harboring uncommon/minor EGFR mutations and HER2-4." (PMID 30410675, 2018). "The continued presence of activating mutations in plasma suggests possible positive selection of the mutations in the EGFR pathway in the corresponding cancers." (PMID 29848757, 2018). "EGFR signaling is frequently altered in several human cancers due to EGFR gene amplification and/or protein overexpression, mutations or in‐frame deletions." (PMID 29124875, 2018). "Drugs such as erlotinib were developed to specifically target constitutively-active EGFR; however, in many cancers, secondary mutations in EGFR rapidly develop to overcome the inhibition." (PMID 30518036, 2018). "Early in vivo and in vitro data reported YH25448 had more potent inhibition of cancer cell growth compared to osimertinib in cancer cells harboring EGFR mutations (L858R/T790 M) with IC50 of 2 nM vs 8 nM and GI50 of 3.6 nM vs 11.8 nM respectively." (PMID 29455654, 2018). "Regardless of mechanism, overexpression of RTKs has been associated with poor outcomes in some cancer patients, such as EGFR and HER3 in breast cancer." (PMID 29455648, 2018). "Together, our findings indicate a complex mechanism underlying PGE2-induced EGF/EGFR signaling and transcriptional control, which plays a key role in cancer progression." (PMID 29599917, 2018). "Several human cancers express EGFRvIII, a variant of EGFR in which a large deletion in its extracellular domain generates a 14 amino acid sequence not found in healthy tissues." (PMID 30416985, 2018). "Overexpression of EGFR has been implicated in all aggressive cancers of epithelial origin, including squamous cell head and neck (90–100%), glioma (90–100%), non-small cell lung (75–90%), colorectal (80–85%), breast (20–30%), and cervical (87–100%)." (PMID 29464066, 2018). "Across all cancer types, PROGENy found a strong association between the activation of EGFR, MAPK, PI3K, and Hypoxia pathways and decreased survival, similar to other signature methods." (PMID 29295995, 2018). "Using Co-II, we study the transient homodimerizations of EGFR and β2-AR in living cells, which have been implicated in several types of cancers and heart diseases." (PMID 30543635, 2018). "The human epidermal growth factor receptor (Her or ErbB) family of receptor tyrosine kinases, which often expresses, amplifies, or mutates in various cancers, constitutes an essential therapeutic target for the disease." (PMID 30212974, 2018).
cancer (continued). "Another investigation, which was carried out in a Caucasian population from the Balkan country, also showed the correlation of EGFR polymorphisms with the histological type of cancer, with the variant alleles being the most frequent in adenocarcinoma." (PMID 30406002, 2018). "The Akt signaling pathway is known to be a downstream target of EGFR, and EGFR activating mutations have been reported to deregulate this pathway in cancer." (PMID 29449326, 2018). "In EGFR-mutated cancers, individual miRNA–mRNA interactions or miRNA/mRNA expression signatures have been characterized." (PMID 30404194, 2018). "Retrospective biomarker identification has led to the stratified use of other anti-cancer therapies that initially failed in unselected trials such as activating EGFR mutations and EGFR TKIs." (PMID 29345617, 2018). "EGFR overexpression has also been associated not only with cancer progression but also with poor prognosis of patients with cancer." (PMID 29215776, 2018). "Very most of these markers are highly organ-specific: for example, EGFR mutations occur mainly in lung adenocarcinomas, while their incidence in other cancer types is limited to anecdotal reports." (PMID 30211169, 2018). "Remarkably, we found this type of mutation in BRAF, ERBB2, JAK2, and EGFR in cancer genomes, suggesting that the dimerization works as a principal mechanism to regulate the activity of these kinases." (PMID 29930381, 2018). "[11C]erlotinib has been proposed as a PET tracer to visualize the mutational status of the epidermal growth factor receptor (EGFR) in cancer patients." (PMID 29888317, 2018). "Preclinical data showed that amplification of EGFR or mutated EGFR vIII induces the overexpression of TF by cancer cells." (PMID 29743116, 2018). "These mutations occur within EGFR exon 18-21,which encodes a portion of the EGFR kinase domain and enables researchers to identify compounds that only recognizes and binds tothe cancer cells." (PMID 30108422, 2018). "The higher sensitivity of cancers with these mutations is due to an increased affinity of EGFR TKIs to the ATP-binding pocket of EGFR as compared with their affinity to WT EGFR." (PMID 29789542, 2018). "One of the most prominent protein kinases is the endothelial growth factor receptor (EGFR) because that kinase is known to be involved in the various cancer-associated processes of uncontrolled cell growth, suppressed apoptosis, and, finally, metastasis." (PMID 29098884, 2018). "High response rates (60–70%) are achieved with the EGFR TKIs in EGFR-mutated cancers and ~60% of partial/complete responses with anaplastic lymphoma kinase (ALK) inhibitors (e.g., crizotinib) in patients with ALK translocations." (PMID 30087852, 2018). "EGFR plays a fundamental signalling role in cell growth and is frequently hyper-activated in human cancers via mutation and/or overexpression." (PMID 30337523, 2018). "While we observed no changes in dual-phosphorylated ERK, we did observe an increase in phospho-AKT levels, a trend previously demonstrated to be associated with mislocalized EGFR and commonly found in cancers such as prostate, ovarian, and breast." (PMID 29464085, 2018). "EGFR overexpression has been reported to be strongly associated with cancer progression and to predict shorter survival in surgically resected non-small cell lung cancer (NSCLC)." (PMID 29950164, 2018). "In agreement, saturation of the endocytic and/or the ubiquitination machinery has been proposed as a mechanism underlying sustained signaling in EGFR‐overexpressing cancer cells." (PMID 29124875, 2018). "Melanomas are derived from the neural crest and therefore have low endogenous EGFR expression, which explains the stunning intrinsic difference in drug sensitivity of two cancer types that are driven by the same mutation." (PMID 29192388, 2018). "The overactivation of epidermal growth factor (EGF) receptor (EGFR) is implicated in various cancers." (PMID 30544639, 2018).
cancer (continued). "While co-administration of EGFR inhibitors enhanced the susceptibility of cancer cells to crizotinib." (PMID 29455663, 2018). "For example, many cancers are driven by mutations in oncogenic kinases, such as the Raf family and EGFR." (PMID 30518036, 2018). "Its overexpression has been previously associated with resistance to EGFR inhibitors in other cancer types including HNSCC." (PMID 29792227, 2018). "Drugs aimed specifically for EGFR have become part of standardised treatment in numerous mutation positive cancers, and is today a included in routine drug regimen in primary CRC." (PMID 30602942, 2018). "Src kinase family has been reported playing an important role in VEGF signaling and effecting proliferation and migration of cancer cell, and Yes and Lyn kinase were highly associated with EGFR signaling." (PMID 29892225, 2018). "EGFR downregulation is associated with enhanced signalling, which can lead to the development of cancer." (PMID 30138363, 2018). "The activation of epidermal growth factor receptor (EGFR) is associated with radioresistance in malignant tumors." (PMID 30414263, 2018). "Overexpression of EGFR is implicated in all aggressive cancers of epithelial origin including squamous cell head & neck (90 – 100%), glioma (90 – 100%), non-small cell lung (75 – 90%), colorectal (80 – 85%), breast (20 – 30%) and cervical cancers." (PMID 29682209, 2018). "Because EGFR is mutated or overexpressed in numerous human cancers, it has become a major prognostic marker and therapeutic target." (PMID 29887852, 2018). "Co-mutations in other cancer-driver genes (oncogenes or tumor suppressor genes) were frequent in EGFR-mutated NSCLCs and few cases harbored concomitant activating and resistance EGFR-mutations before TKI-treatment." (PMID 29899852, 2018). "One hundred and thirty-five patients were male, 157 patients had a history of smoking, 153 patients had an ECOG PS of 0–1, the median number of previous treatment was 2, 42 patients had SQ carcinoma, and 37 patients had EGFR mutation." (PMID 29470536, 2018). "On the exemplary system we described library preparation procedure for targeted resequencing and cancer mutation detection in single EGFR gene." (PMID 28583065, 2017). "Because EGFR is mutated or overexpressed in a variety of human cancers, it has become a major prognostic marker and therapeutic target." (PMID 29268862, 2017). "EGFR is commonly overexpressed or activated via gene amplified and/or gain of function mutations in a variety of cancers." (PMID 29211022, 2017). "The better combination effect observed in patients with acquired T790M mutation is probably because their cancer cells still rely heavily on EGFR and its downstream signaling for growth and survival." (PMID 28977977, 2017). "We studied the mutational probability landscape of EGFR in two different non- NSCLC cancer types: LUAD and LSCC." (PMID 28436422, 2017). "In the present study, we investigated the radiosensitizing effect of miR-200c and the mechanism of radiosensitization in a panel of human cancer cell lines with activated EGFR-associated signaling." (PMID 29029445, 2017). "Ion Torrent technology (Ampliseq cancer panel) performed better than GS-454 (5 amplicons covering KRAS/EGFR hot spot) which failed in identifying KRAS mutations in four samples." (PMID 29221448, 2017). "While EGFR is amplified or mutated, DNA synthesis and cell proliferation will be abnormal and lead to cancer." (PMID 28630865, 2017). "Rap1 (in KEGG) and ras (in KEGG) signaling are activated by lung cancer oncogene CRKL whose focal amplification (secondary mutation) was reported to be associated with acquired resistance to EGFR inhibitor." (PMID 28288164, 2017). "We recently observed that exposure of TNBC cells overexpressing EGFR to s-CD95L induces association of CD95 with EGFR, thereby promoting cell migration and metastatic dissemination of these cancer cells." (PMID 29021794, 2017).
cancer (continued). "Numerous genomic alterations have been found in correlation with oncogenesis and cancer progress, such as EGFR mutations, ALK-fusions, and KRAS mutations." (PMID 29285248, 2017). "Several EGFR mutations are known to render cancer cells hypersensitive (e.g., L858R, exon 19 deletions) or resistant (e.g., T790M) to targeted inhibitors." (PMID 28417948, 2017). "This notion is further supported by the observation that cancer patients treated with EGFR antagonists suffer not only from a wide range of side effects caused by loss of EGFR function on epithelial cells but also become more susceptible to infections." (PMID 29045902, 2017). "Further, treatment with MM151 can overcome cancer cell acquired resistance to the anti-EGFR mAbs cetuximab or panitumumab, which is sustained by the emergence of EGFR extracellular domain (ECD) mutations." (PMID 29137301, 2017). "AKT and p44/42-MAPK signalling pathways are major downstream effectors of the EGFR signalling pathway associated with survival and proliferation of cancer cells." (PMID 28445969, 2017). "The recently developed multi-kinase inhibitor SKLB1206 showed promising results in inhibiting not only EGFR with gefitinib-sensitive and -resistant mutations but also showed considerable inhibition potency against ErbB2 and ErbB4 in cancer cell lines." (PMID 28417948, 2017). "EGFR is a highly variable gene, which is thought as the fourth most highly mutated gene in a compendium of common cancer genes." (PMID 29156842, 2017). "Autophagy is a process of self-digestion that is inhibited by EGFR allowing cancer cells to survive under stresses that would normally cause death and become resistant to chemotherapy." (PMID 28338617, 2017). "Despite the extensive molecular and functional characterization of EGFR and a continuing effort in pursuing anti-EGFR cancer therapies, the molecular mechanism underlying the regulation/dysregulation of EGFR expression remains poorly explored." (PMID 28947780, 2017). "PI3K and AKT activity is also linked to EGFR-dependant TF upregulation that is associated with induction of epithelial to mesenchymal transition, a key feature of cancer stem cell activity." (PMID 28033108, 2017). "Cancer cells exhibit various mutations that increase the expression/activation of growth factor (GF) receptor proteins such as epidermal growth factor receptor (EGFR)." (PMID 28481268, 2017). "Amplification or uncontrolled activation of EGFR signaling has been implicated in the invasion and metastasis of many cancers." (PMID 29212252, 2017). "The cancer cells express either wild type EGFR or harbor distinct EGFR mutations in exons 19, 20 and 21 that are known to influence targeted drug sensitivity in vivo." (PMID 29296175, 2017). "The epidermal growth factor receptor (EGFR) is constitutively activated either by somatic mutations or by overexpression in multiple cancer entities." (PMID 28507280, 2017). "While Erlotinib and Gefitinib are in use clinically, each is associated with a high rate of relapse in patients due to further molecular alterations that develop, such as the 790M mutation to EGFR, which renders the cancer resistant." (PMID 29113413, 2017). "EGFR is another molecule which has been clearly shown positively associated with cancer invasion by activating downstream PI3K/Akt signaling and inducing EMT." (PMID 28903339, 2017). "In cancers, activating mutations to the EGFR are correlated with higher expression levels of CYCLIN D." (PMID 28513565, 2017). "This analysis of the efficacy of EGFR-TKIs provides preclinical information to inform the proper selection of EGFR-TKIs for the treatment of patients with cancers harboring EGFR mutations." (PMID 29285266, 2017). "Expression of the cancer-derived EGFR mutant, commonly known as EGFRvIII, also caused an increase in MYC above background levels." (PMID 28152508, 2017).
cancer (continued). "EGFR is a highly N-linked glycosylated cell surface glycoprotein that plays a critical role in the majority of human cancers correlating with increased cell growth, proliferation, and differentiation." (PMID 29069815, 2017). "Overexpression of EGFR has also been linked to anticancer drug resistance and greater aggression of breast, lung, and other cancers." (PMID 29164150, 2017). "Incorporation of KRAS and now the extended RAS mutation panel as a predictive marker for anti-EGFR based therapy for CRC is landmark advancement in the pursuit of personalized care for patients with cancer." (PMID 28740573, 2017). "EGFR abnormal expression occurs in many cancer patients mostly due to its mutation, especially in NSCLC." (PMID 28915650, 2017). "Ganetespib has demonstrated its efficacy not only in monotherapy, but also in combination with other drugs in various cancer types driven by different oncogenic mutations such as mutant EGFR and KRAS mutant NSCLC." (PMID 28914774, 2017). "Our results suggested that miR-200c is an important modulator of the EGFR pro-survival cell signaling network implicated in the radiation response of human cancer cells." (PMID 29029445, 2017). "Direct gene sequencing is the standard method used for detection of EGFR mutations in cancer, however, its many limitations, such as low sensitivity and length of procedure (several days), restrict its use in the clinic." (PMID 28489575, 2017). "EGFR is a cell surface receptor tyrosine kinase that is often overexpressed or mutated in human cancers, resulting in increased proliferation, migration and angiogenesis." (PMID 28656962, 2017). "Expression of PCNA is associated with the expression of epidermal growth factor receptor, which itself is a survival factor for many cancers, including RCC." (PMID 28405545, 2017). "Although this being an unexpected effect, the increase of EGFR gene expression on cancer cells can take it more susceptible to tyrosine kinase inhibitors, indicating a potential synergic effect of complex 2 with this class of drugs." (PMID 29262647, 2017). "As mentioned in the previous research, over-expression of EGFR and cyclin D1 molecular markers is associated with cancer." (PMID 29354245, 2017). "In terms of mutations to EGFR-pathway proteins, the efficacy of anti-EGFR therapy has been best studied in cancers with K-RAS mutations, with the consensus that these cancers will display primary resistance to EGFR inhibitors." (PMID 28513565, 2017). "We found that the gastrin-releasing peptide receptor, which is implicated in EGFR-associated cancers, also triggered iRhom2 phosphorylation." (PMID 29045841, 2017). "Mutations in the EGFR gene that constitutively activate the receptor frequently occur in human cancers." (PMID 28574446, 2017). "Considering the heterogenic effects EGFR mutations, we opted to restrict our evaluation to changes in EGFR gene transcription that occur because of EGFR amplification in cancer cell lines." (PMID 28276478, 2017). "In our previous reports, we observed that overexpressing miRNAs was associated with downregulated EGFR-associated signaling and increased radiosensitivity of human cancer cells that have activated EGFR and/or co-activation of PI3K-Akt signaling." (PMID 29029445, 2017). "Autophagic degradation of EGFR was caused by the treatment of cancer cells with the protein kinase CK2 inhibitor CX-4945 or with the herbal plant derivative celastraol." (PMID 28338617, 2017). "We previously demonstrated that the lymph node ratio (LNR) is a prognostic factor associated with EGFR expression, among first priority genes amplified or overexpressed in cancer." (PMID 29088808, 2017). "Some authors reported that ALK rearrangements were more common in patients with poorly differentiated adenocarcinoma whilst EGFR mutations were typical of well-differentiated cancers." (PMID 28938691, 2017).